CRP (C-reactive protein)
Diseases named in the same sentence as CRP in open-access papers (continued):
Sharing a sentence is not in itself a finding about the gene and the disease.
empyema (22 papers, 2010 to 2025). An accumulation of pus in a body cavity, usually the pleural space. "Conversely, the presence of empyema was associated with a reduction in CRP by 20.68%, 95% CI (4.3%, 34.3%)." (PMID 41523477, 2025). "In the Finnish study, prolonged fever and persistence of high serum CRP during hospitalization were associated with the development of empyema." (PMID 20670443, 2010). "Baseline CRP was similar in those diagnosed with empyema (192.20 mg/L, 95% CI (147.67, 236.72)) to those diagnosed with a complicated parapneumonic effusion (203.48 mg/L, 95% CI (185.50, 221.44)), p=0.60." (PMID 41523477, 2025). "A retrospective observational analysis was conducted to evaluate trends in CRP levels in patients undergoing treatment for parapneumonic effusion or empyema." (PMID 41523477, 2025). "Patients with empyema had higher absolute neutrophil count, higher levels of C-reactive protein, procalcitonin, and ferritin, and lower serum albumin levels." (PMID 40868554, 2025). "An observational analysis was performed on patients who were treated for either a parapneumonic effusion or empyema by tube thoracostomy and possessed at least two sequential CRP measurements." (PMID 41523477, 2025). "A declining CRP is an insufficient standalone indicator of treatment success in parapneumonic effusion and empyema." (PMID 41523477, 2025). "Diagnosing empyema can be challenging due to an insidious onset, but typically presents with fevers, leukocytosis and elevated C-reactive protein (CRP)." (PMID 39483118, 2024). "Pleural fluid CRP was significantly higher in the empyema and parapneumonic groups compared to tuberculous and malignant effusions." (PMID 35874904, 2022). "We found that pleural fluid and serum CRP levels were higher in the parapneumonic and empyema groups compared to tuberculous and malignant effusions." (PMID 35874904, 2022). "It is evident from our study that pleural fluid CRP is a very rapid and cost-effective tool to differentiate parapneumonic effusion and empyema from other exudative effusions." (PMID 35874904, 2022). "In the CPPE and empyema patients, the serum CRP and serum IL-6 levels were significantly elevated, and these results were consistent with those of previous reports." (PMID 31215423, 2019). "Pleural fluid CRP was found to represent a useful marker for the diagnosis of empyema; using a cut-off point of 4.91 mg/dL, pleural fluid CRP presented 63.6% sensitivity and 89.3% specificity for the diagnosis of empyema." (PMID 30470216, 2018). "Pleural fluid CRP levels were significantly higher in patients with empyema, parapneumonic effusion, and tuberculous effusion compared with patients who had malignant or transudate effusions." (PMID 30470216, 2018). "In the differentiation of empyema, a combination of pleural fluid presepsin and CRP yielded the highest accuracy rate." (PMID 30470216, 2018). "High levels of pleural fluid presepsin were found in cases of empyema and parapneumonic effusion; this closely resembles the previously reported pattern of pleural fluid CRP levels." (PMID 30470216, 2018). "The combination of pleural fluid PCT levels of < 2.57 ng/mL and pleural fluid CRP levels of > 4.91 mg/dL yielded the second highest accuracy rate (87.9%) in the differentiation of empyema." (PMID 30470216, 2018). "CRP was a moderately good marker for differentiating between empyema and other types of effusions (2.31 mg/dL cut-off value, 83.3% sensitivity, 74.7% specificity, 8.3% positive predicted value, and 99.3% negative predicted value)." (PMID 27194820, 2016). "Procalcitonin level was significantly higher (by 1.7 fold) in empyema than in malignant effusions, matched for CRP, indicating that procalcitonin is superior to CRP for the identification of pleural infection." (PMID 23251353, 2012).
empyema (continued). "Moreover, with the exception of CRP in pneumothorax and empyema, in which significant increases can be seen, CRP, pleural fluid CRP, and gradient CRP have been proposed as markers for the discrimination of Uncomplicated Parapneumonic Effusion (UCPPE) from Complicated Parapneumonic Effusion (CPPE)." (PMID 37873776, 2023). "Patients with serum CRP lower than 32.6 mg/dl may perform second serum test and the combination of neutrophil-associated proteins (calprotectin or NGAL) and CRP could provide useful information for CPPE and empyema diagnosis." (PMID 31215423, 2019). "When diagnosing empyema, the marker with the highest sensitivity was pleural fluid presepsin (cut-off: 754 pg/mL; sensitivity: 90.9%, specificity: 74.4%) and that with the highest specificity was pleural fluid CRP (cut-off: 4.91 mg/dL; sensitivity: 63.6%, specificity: 89.3%)." (PMID 30470216, 2018). "The combination of serum calprotectin and CRP constitutes a more highly sensitive and specific assay for identifying CPPE and empyema." (PMID 31215423, 2019). "The levels of CRP and IL-6 were significantly higher in pleural fluid from patients with CPPE and empyema." (PMID 31215423, 2019). "When we set the cutoff value of serum CRP was 32.6 mg/dl, the sensitivity was 100% for identifying CPPE/empyema, which approach can identify all severe patients." (PMID 31215423, 2019). "The AUC values for distinguishing CPPE and empyema from UPPE were 0.775 for serum NGAL, 0.765 for serum calprotectin, and 0.766 for serum CRP, and 0.717 for serum IL-6." (PMID 31215423, 2019). "When combined with serum CRP, the sensitivity and specificity of serum calprotectin for identifying CPPE and empyema were the highest at 73.52% and 80.55%, respectively." (PMID 31215423, 2019). "Adenosine deaminase (ADA), C Reactive Protein (CRP) and granulocyte count are all used in the differential diagnosis of tuberculous effusions, parapneumonic effusions and empyema." (PMID 28545517, 2017). "The diagnostic value of CRP in identifying PPE from other types of effusion, particularly CPPE/empyema was not higher than those three serum biomarkers (NGAL, calprotectin, BPI)." (PMID 31215423, 2019). "Thus, the combination of the serum levels of CRP and calprotectin improved the sensitivity to 73.52% and specificity to 80.55% for identifying CPPE and empyema." (PMID 31215423, 2019). "Although PCT alone was not useful for the differentiation of empyema, it was found that this marker can be a useful tool when combined with CRP or presepsin." (PMID 30470216, 2018). "The combination of PCT and CRP also showed better accuracy than the combination of PCT and presepsin in distinguishing between infectious and non-infectious pleural effusion, parapneumonic pleural effusion, and other types of effusions (excluding empyema in both groups)." (PMID 30470216, 2018). "Serum CRP levels above 32.6 mg/dl were evident in 8 cases in the CPPE and empyema group but in no cases in the UPPE group." (PMID 31215423, 2019).
gastroenteritis (22 papers, 2013 to 2025). An inflammatory disorder that affects the upper and lower gastrointestinal tract. "The mesenteric blood flow based on MRI has been linked with intestinal inflammation in CD patients, with a positive correlation between the blood flow and C-reactive protein and fecal calprotectin." (PMID 41210880, 2025). "Gastroenteritis was associated with higher CRP and creatinine values (p < 0.05 each)." (PMID 34083692, 2021). "Multivariate logistic regression analysis showed that both gastroenteritis, cranio-bulbar affection, need for mechanical ventilation (MV), disability score >4, and absent motor and sensory responses were significantly associated with high serum CRP level >6mg/dl." (PMID 29780224, 2018). "This study demonstrates that low serum circulating 25(OH)D3 is associated with intestinal inflammation (FC) in IBD and systemic inflammation (CRP) in UC." (PMID 31083541, 2019). "The mean CRP was 5.3 ± 11.4 mg/dl in patients with AA, 10.6 ± 6.8 mg/dl in patients with gastroenteritis and 0.6 ± 0.9 mg/dl in the control group." (PMID 28033410, 2016). "Gastroenteritis score was positively correlated with leukocyte and platelet count and CRP level in patient’s group." (PMID 25793071, 2014). "Gastroenteritis score was positively correlated with leukocyte (r=0.670, P<0.01) and platelet count (r=0.159, P<0.05) and CRP level (r=0.256, P<0.01) in patients group." (PMID 25793071, 2014). "Intestinal inflammation is known to impair growth and development, as evidenced by elevated inflammatory markers such as C-reactive protein (CRP) and interleukin-6 (IL-6) be elevated in children with giardiasis and a link between chronic inflammation and stunting." (PMID 37816031, 2023). "There is a spike in CRP noted with a small increase in nucleosome concentrations in May of 2020 for this patient which coincided with an episode of severe gastroenteritis that required ICU hospitalization for 2 days." (PMID 34187493, 2021). "By multivariate logistic regression analysis, it was found that both preceding infection with gastroenteritis, craniobulbar affection, need for MV, disability score > 4, and absent motor and sensory nerve responses were significantly related to high serum CRP level > 6 mg/dl." (PMID 29780224, 2018). "On doing a multivariate regression analysis, it was found that serum CRP level > 6 mg/dl was significantly associated with preceding infection (gastroenteritis), need for MV, disability score > 4, and absent both motor and sensory nerve responses." (PMID 29780224, 2018). "The results of this study support the hypothesis that in GBS patients, gastroenteritis, craniobulbar affection, need for MV, disability score >4, and absent motor and sensory nerve responses were significantly related to high serum CRP level." (PMID 29780224, 2018). "Clinically, C. concisus have recently been associated with prolonged diarrhoea in 80% of patients with culture-positive C. concisus gastroenteritis, whereas the pathogen gives rise to an elevated C-reactive protein level only about half as often as C. jejuni/coli (48% compared to 94%)." (PMID 23819746, 2013). "Fecal myeloperoxidase (MPO) and neopterin (NEO) were markers of intestinal inflammation whereas plasma lipopolysaccharide-binding protein (LBP) and C-reactive protein (CRP) were assessed as markers of systemic inflammation." (PMID 39775265, 2024). "boulardii administered to a child suffering from gastroenteritis showed a considerable rise in the IgA levels and a reduction in CRP (C-reactive protein) levels." (PMID 35628700, 2022). "In this study, patients with high ESR, CRP and PLT account for 53.2%, 38.1% and 36%, respectively, indicated activity of intestinal inflammation." (PMID 30758468, 2019). "The clinical symptoms of the patient with absence of leucocytosis and moderately elevated C-reactive protein-levels indicated diagnosis of gastroenteritis." (PMID 27610052, 2016).
sinusitis (22 papers, 2006 to 2026). An acute or chronic inflammatory process affecting the mucous membranes of any sinus cavity. "Sinusitis (we showed that the diagnostic Berg/Carenfelt algorithm reduced the numbers of individuals eligible for antibiotics, and C-reactive protein (CRP) may also be helpful)." (PMID 40205913, 2025). "Increased C-reactive protein values were observed in 74.3% of the cases, also with a higher frequency in patients with AO (83.3%) or those with both otitis and sinusitis (81.8%)." (PMID 38893057, 2024). "After full clinical work-up, five of these patients had some signs of inflammation (elevated CRP, n = 3; sinusitis, n = 1; or elevated ANA and ANCA titers, n = 1)." (PMID 36860843, 2023). "CRP rarely shows anything, but if it is high and symptoms clearly tell me it is sinusitis, those are some of the few times I consider using antibiotics." (PMID 37902260, 2023). "The other half thought the test was redundant because an elevated CRP was perceived as uncommon in sinusitis." (PMID 37902260, 2023). "Some authors have reported on the use of laboratory tests, including sedimentation rate, white blood cell counts, and C-reactive protein levels, to help diagnose acute sinusitis." (PMID 22007246, 2012). "The impact on practice management was demonstrated as the use of CRP lowered antibiotic prescribing for sinusitis." (PMID 16670014, 2006). "They viewed sinusitis as a clinical diagnosis and believed there was no guarantee for elevated CRP even with a bacterial infection." (PMID 37902260, 2023). "Hence, our study aims to study the kinetics of serum CRP levels in patients undergoing in-patient care for CAM and compare them with serum CRP levels in COVID patients suffering from sinusitis without mucormycosis." (PMID 38800245, 2024).
conjunctivitis (21 papers, 2020 to 2025). Inflammation of the conjunctiva of the eye. "On day 3 & 4, she experienced bilateral conjunctivitis, hypotension (66/47 mmHg), and a high CRP level." (PMID 36865693, 2023). "Treatment resulted in reduced inflammatory symptoms such as rash severity, conjunctivitis, as well as reduced C-reactive protein (CRP) and serum amyloid A (SAA) levels, and over time, reduced organ inflammation." (PMID 35567665, 2022). "Blood test parameters, including white blood cell, neutrophil, procalcitonin C, C-reactive protein, and lactate dehydrogenase levels, have also been reported to be higher in patients with conjunctivitis." (PMID 32703010, 2021). "Diarrhea and conjunctivitis at the initial presentation with significantly elevated CRP, Pro-BNP and blood pH concentrations were found to be a potential predisposing factor for decreased cardiac function while Pro-BNP and pH were independent risk factors for MIS-C." (PMID 37085781, 2023). "Separate examination of potential predisposing factors for decreased cardiac function revealed that diarrhea (15.2% and 40%, respectively) and conjunctivitis (45.5% and 75%, respectively) occurred more commonly in these patients in parallel with elevated CRP, Pro-BNP concentrations, and pH." (PMID 37085781, 2023). "If a child with suspected KD has conjunctivitis and CRP ≥ 40.1 mg/L, it is KD." (PMID 34682194, 2021). "In all patients, a prompt clinical response (particularly disappearance of rash and conjunctivitis) was observed along with a decrease in inflammatory markers—erythrocyte sedimentation ratio (ESR), C-reactive protein (CRP) and serum amyloid A (SAA)." (PMID 33603750, 2020). "Among the high-risk population (n = 68), in univariate analysis, face rash, cervical lymphadenopathy, conjunctivitis, catarrhal symptoms, decreased WBC, and CRP were significantly observed in AR." (PMID 32330153, 2020). "In our case study, a 12-year-old boy exhibited persistent fever, bilateral non-purulent conjunctivitis, edematous limbs, unresponsive shock, low levels of albumin, significantly elevated levels of CRP." (PMID 39093792, 2024). "The main manifestations in this case were recurrent fever, urticarial-like rash, and conjunctivitis without obvious inducement, accompanied by elevated neutrophils, CRP, SAA, and ESR." (PMID 36765385, 2023).
cyst (21 papers, 2009 to 2025). A sac-like closed membranous structure that may be empty or contain fluid or amorphous material. "Laboratory panels also broadened to incorporate inflammatory biomarkers (e.g., CRP, γ-GT) and cyst fluid tumor antigens (e.g., CEA), demonstrating an awareness of the interplay between inflammatory, hemorrhagic, and neoplastic processes." (PMID 40709994, 2025). "When parameters were compared according to rupture status, preoperative CRP levels were significantly higher in the ruptured cyst group (p < 0.05)." (PMID 40809602, 2025). "However, when the cyst grows larger, it may cause symptoms such as hepatomegaly, upper abdominal quadrant pain, fever, nausea, vomiting, leukocytosis, and increased C-reactive protein (CRP)." (PMID 40671932, 2025). "They noted that elevated s-DD and a cyst diameter >5 cm yielded the highest sensitivity (82%), while the presence of nausea and vomiting alongside elevated c-reactive protein (CRP) had the highest specificity (>85%)." (PMID 39519217, 2024). "Laboratory data indicated high levels of inflammation (white blood cell 12,000/μL, C-reactive protein 16.0 mg/dL), and computed tomography demonstrated a large intrapulmonary cyst located in the middle of the right lower lobe, with some fluid collection." (PMID 38780682, 2024). "The mean (± SEM) levels of CRP (mg/L) were significantly higher in the OMA group (1.38 ± 0.11) than those in the Cyst group (0.86 ± 0.08, P < 0.01) and Control group (0.72 ± 0.15, P < 0.0001)." (PMID 31888633, 2019). "Elevated D-dimer and cyst diameter larger than 5 cm yielded highest sensitivity (82% for each); whereas the presence of nausea and vomiting and elevated CRP had the highest specificity (85% and 88%, respectively)." (PMID 26854140, 2015). "The findings showed significant decreases in the thickness of granulosa layer, the number of corpus luteum, and cyst formation, as well as an increase in C-reactive protein (CRP), in the PCOS group compared to the control group (that received no drug injection or extract treatment)." (PMID 35145892, 2022). "Because of his leg swelling and tenderness, the elevated CRP and the diagnosed Baker’s cyst in ultrasound, an incarcerated Baker’s cyst with ruptured cyst or bleeding in the cyst with suspected resulting compartment of the leg was our second differential diagnosis." (PMID 26696095, 2015). "Five patients had a definite cyst infection based on cyst aspiration, and three patients a probable cyst infection based on the presence of all of the following five factors: fever, abdominal pain, increased CRP, the absence of cyst bleeding and the absence of any other possible cause of fever." (PMID 29568734, 2018). "A peptide derived from CRP was identified in IEF-fractionated cyst fluid, while peptides derived from all biomarker candidates, except for CRP, were identified in both unfractionated and IEF-fractionated cyst fluid." (PMID 29513714, 2018). "Neither cyst diameter, cyst location nor laboratory signs of infection prior to intervention (C-reactive protein > 0.5 mg/dl or white blood cell count > 9 G/l) were associated with complications due to intervention in multivariate logistic regression analysis." (PMID 28877270, 2017). "CyI was definite if confirmed by cyst puncture, and probable if 4 criteria were met: 3-day fever, loin/liver tenderness, C-reactive protein (CRP) plasma levels >50mg/L and no CT evidence for CyH." (PMID 27529555, 2016).